KLF15 (KLF transcription factor 15)
Diseases named in the same sentence as KLF15 in open-access papers (continued):
Sharing a sentence is not in itself a finding about the gene and the disease.
tumor (continued). "Expression of KLF15 was found to be abnormally high in LADC tissues and cells compared with adjacent non-tumorous tissues, and was correlated with tumor TNM stage and tumor differentiation (P = 0.003, P = 0.001, respectively)." (PMID 29299121, 2017). "Heatmap analysis of gene expression in adherent cells and stem‐like tumor spheres revealed a negative correlation between YY2 and stem‐related factors, including CD44, SOX9, SALL2, KLF15, OCT4 (also known as POU class 5 homeobox 1 or POU5F1), MYC, ASCL1, and POU3F2." (PMID 37300334, 2023).
cancer (16 papers, 2017 to 2025). A tumor composed of atypical neoplastic, often pleomorphic cells that invade other tissues. "Metabolome data analysis derived from 82 metabolites revealed that KLF15 elevates the following metabolic pathways that have been implicated in a multitude of cancers including BrCa." (PMID 36347994, 2022). "Dysregulation of KLF2 and KLF15 has been reported to play vital roles in a variety of human cancers." (PMID 35033064, 2022). "Thereby, the discovery of the upregulating modulation of TFAP2A-AS1 in this study is another evidence of the inhibitory role of KLF15 in human cancers." (PMID 34727954, 2021). "Previous reports have demonstrated that KLF15 plays the role both in promoting cancer and suppressing cancer, then we conducted more than 3 times experiments to verify the role of KLF15 in LADC." (PMID 29299121, 2017). "The function of the KLF15/lncRNA axis has been discussed in other cancer pathogenesis." (PMID 38273088, 2024). "Moreover, our data show that particular IRX genes and KLF15 operate in a breast (cancer) specific regulatory network." (PMID 38391914, 2024). "Moreover, knockdown of LINC00689 reversed the inhibiting effects of KLF15 overexpression on cancer cell proliferation, migration, and invasion." (PMID 38273088, 2024). "The results all demonstrated that KLF15 played a vital role in promoting LADC cancer." (PMID 29299121, 2017). "Recent in vitro studies have found that KLF15 may have anti-proliferative effects on carcinoma cells in a range of cancers, including those of the endometrium, pancreas, and breast." (PMID 29299121, 2017). "This suggested that KLF15 might participate in key signaling pathway involved in anti-cancer drug metabolism in BrCa and might play important role in the potency and detoxification of anti-cancer drug administration to cancer patients." (PMID 36347994, 2022). "The results showed that overexpression of KLF15 decreased the proliferative rate of CRC cells and also inhibited the migratory and invasive abilities of cancer cells." (PMID 38273088, 2024). "KLF15 was substantially downregulated in COAD tissues based on other variables, such as sample types, individual cancer stages, and nodal metastasis status." (PMID 38273088, 2024). "Several studies have reported the reciprocal relationship between KLF15 expression and cell cycle regulators, such as E2F1 and cyclin-cdk inhibitors p21Cip1/p57kip2, in different types of cancer." (PMID 32850313, 2020). "Even though there are no current reports on KLF15 regulating chemo-metabolism in cancer, research work by Han S. and coworkers identified KLF15 as regulator of metabolism and elimination of hepatic endobiotics and xenobiotics (EXM) through various pathways." (PMID 36347994, 2022). "The transcription factor KLF15, also called kidney-enriched KLF (KKLF), has been proven to play a role in inhibiting proliferation and diversification of carcinoma cells, including those of the endometrium, pancreas and breast, but the involvement of KLF15 in LADC has not previously been studied." (PMID 29299121, 2017). "However, in other cancers, KLF3 and KLF15 might have carcinogenic properties." (PMID 41155227, 2025).
infection (12 papers, 2019 to 2025). The state of being infected such as from the introduction of a foreign agent such as serum, vaccine, antigenic substance or organism. "KLF15 is also an important stress-induced gene in fish, and experimental infection with VNN in European sea bass has been reported to activate a strong stress response." (PMID 40069747, 2025). "In conclusion, this research revealed that KLF15 expression is important during acute infection of mice but less important during explant-induced reactivation from latency." (PMID 40872334, 2025). "We differentiated these cells in culture and then knocked down human KLF15 (hKLF15) expression in the mature human adipocytes using adenoviral infection of Klf15 shRNA compared with control shRNA infection." (PMID 38949025, 2024). "Silencing expression of the KLF15 protein hindered Herpes Simplex Virus 1 productive infection, and KLF15 protein levels increase during productive infection." (PMID 39599791, 2024). "Restoration of KLF15 was completed through infection of KLF15 containing lentivirus selected by puromycin, and was confirmed by RT-PCR and Western blotting." (PMID 36347994, 2022). "Future studies will focus on delineating the mechanism by which KLF15 regulates productive infection as well as certain aspects of reactivation from latency." (PMID 34203849, 2021). "Relative to mock-infected cells, KLF15 protein expression was readily detected at 16 h of infection." (PMID 34203849, 2021). "Chromatin immunoprecipitation studies have demonstrated that GR and KLF15 occupy ICP27 promoter sequences during productive infection." (PMID 34835102, 2021). "The studies in this report demonstrated BoHV-1 and HSV-1 stimulate KLF15 steady-state protein levels during late stages of productive infection." (PMID 34203849, 2021). "New studies demonstrated that silencing KLF15 impaired HSV-1 productive infection, and KLF15 steady-state protein levels were increased at late stages of productive infection." (PMID 34203849, 2021). "In summary, these studies demonstrated there is a correlation between efficient BoHV-1-productive infection and increased KLF15 protein steady-state levels at late times after infection." (PMID 34203849, 2021). "Immunofluorescence was subsequently performed to compare KLF15 protein expression in infected Vero cells at 16 h after infection versus mock-infected cells." (PMID 34203849, 2021). "Previous studies demonstrated that cotransfecting GR and KLF15 with BoHV-1 genomic DNA stimulated productive infection more efficiently than KLF15 or GR alone." (PMID 34203849, 2021). "HSV-1-infection-stimulated KLF15 promoter activity was approximately 4-fold in Vero cells, which was significantly higher than in mock-infected cells." (PMID 34203849, 2021). "Collectively, these studies indicated HSV-1-productive infection increased KLF15 steady-state protein levels at late times after infection of Vero and SH-SY5Y cells." (PMID 34203849, 2021). "Western blot analysis indicated KLF15 steady-state protein levels increased as a function of time after infection of Vero cells." (PMID 34203849, 2021). "In summary, these studies demonstrated GR and KLF15 occupy ICP27 promoter sequences during productive infection." (PMID 34835102, 2021). "Since GR and KLF15 stimulate BoHV-1 productive infection and transactivates key viral promoters, stressful stimuli can trigger reactivation from latency." (PMID 34203849, 2021). "Western blot studies revealed significantly higher KLF15 steady-state protein levels at 16 and 24 h after infection." (PMID 34203849, 2021). "In the absence of other viral genes, ICP0 and bICP0 transactivated KLF15 promoter activity, which correlated with increased KLF15 steady-state protein levels during productive infection." (PMID 34203849, 2021). "The GR and KLF15 are frequently expressed in the same TG neuron during reactivation and cooperatively stimulate productive infection and IEtu1 promoter activity." (PMID 31134079, 2019).
infection (continued). "Notably, virus shedding during acute infection was reduced in male and female KLF15−/− mice relative to wild-type (wt) age-matched littermates." (PMID 40872334, 2025). "Finally, HSV-1 induces (KLF15) steady state protein levels during productive infection, and silencing KLF15 significantly reduces viral replication." (PMID 35746756, 2022). "While our studies predicted KLF15 stimulates viral gene expression during productive infection, KLF15 may also enhance additional steps during the late stages of productive infection." (PMID 34203849, 2021). "Furthermore, the HSV-1 ICP0 promoter is cooperatively transactivated by GR and KLF15, and productive infection is impaired when cells are treated with a GR-specific antagonist." (PMID 34203849, 2021). "Based on these studies, we hypothesized infection is a stressful stimulus that increases KLF15 expression and enhances productive infection." (PMID 34203849, 2021). "In fact, KLF15 was primarily detected in the cytoplasmic extract 24 h after infection with BoHV-1." (PMID 34203849, 2021). "In addition to DEX activating GR, KLF15 can cooperate with the progesterone receptor and/or the androgen receptor to activate bovine herpesvirus (BoHV-1) immediate early gene expression, which enhances productive infection." (PMID 40872334, 2025). "At 16 h and 24 h after infection of SH-SY5Y cells, there was also a significant increase in KLF15 steady-state protein levels when compared to cells mock-infected for 2 or 24 h." (PMID 34203849, 2021). "As expected, GR and KLF15 strongly stimulated productive infection, and DEX further enhanced productive infection." (PMID 33430186, 2021). "Additional DEX induced transcription factors, SPDEF (Sam-pointed domain containing Ets transcription factor), Krüppel-like transcription factor 15 (KLF15), KLF4, KLF6, and GATA6, stimulate productive infection and certain key viral promoters." (PMID 31134079, 2019). "In the context of productive infection, we cannot rule out the possibility that other viral genes play a role in increasing KLF15 steady-state protein levels." (PMID 34203849, 2021). "KLF15 was primarily localized to the nucleus following infection of cultured cells with HSV-1, but not BoHV-1." (PMID 34203849, 2021). "In contrast to MDBK cells, KLF15 steady-state protein levels were not significantly higher after infection." (PMID 34203849, 2021). "Furthermore, lower levels of HSV-1 virus shedding in TG were detected at 4- and 8-days post-infection regardless of sex whereas lower levels of viral DNA were detected only in TG of female KLF15−/− mice." (PMID 40872334, 2025). "Decreased activity of the hepatocyte KLF15-CBG module, as occurs during inflammatory stimulation, might be a mechanism that serves to augment inflammatory tone during early phases of infection or tissue injury." (PMID 35263131, 2022). "Since silencing KLF15 interfered with HSV-1 replication and over-expressing GR and KLF15 stimulated BoHV-1 replication, we predict GR and KLF15 interactions with viral promoters have biological relevance during productive infection and following stressful stimuli." (PMID 34203849, 2021). "However, the effects of KLF15 on HSV-1-productive infection had not been examined." (PMID 34203849, 2021). "In contrast to KLF15, KLF4 protein levels were not increased following infection of Vero or SH-SY5Y." (PMID 34203849, 2021). "When cultures were transfected with 50 nm of the KLF15 siRNA and then infected with HSV-1, there were no detectable plaques at 24 h after infection." (PMID 34203849, 2021).
kidney diseases (7 papers, 2018 to 2023). "Although several KLF members including KLF2, KLF4, KLF6, and KLF15 in glomerular endothelial cells or podocytes have been linked to kidney diseases, all these reported KLF members serve as renal protectors." (PMID 30948420, 2019). "Another paper mentioned that keto-analogues and LPD increased the expression of Kruppel-like factor-15 (KLF15), a transcription factor proved to reduce cardiac fibrosis, thus reduced the severity of kidney disease in a remnant model." (PMID 30975176, 2019). "In this review, we summarized the diverse roles of KLF15 and elaborated on its protective effects in kidney diseases, providing new insights into the progression and therapy of CKD." (PMID 31523196, 2019). "In this paper, we investigate the expression of cardiac KLF15 in an experimental model of kidney disease induced by subtotal nephrectomy (STNx)." (PMID 29970016, 2018). "Numerous studies have confirmed that KLF15 has a protective effect against kidney diseases." (PMID 37833977, 2023). "To date, the studies of KLF15 in kidney disease have focused on its role in kidney fibrosis." (PMID 29970016, 2018).
metabolic disease (7 papers, 2018 to 2025). A congenital disorder (due to inherited enzyme abnormality) or acquired (due to failure of a metabolically important organ) disorder resulting from an abnormal metabolic process. "Taken together, KLF15 was involved in metabolic diseases by regulating gluconeogenesis, lipid, amino acid catabolism, bile acids, endobiotic and xenobiotic metabolism." (PMID 36937859, 2023). "This suggests that KLF15 may emerge as a major therapeutic target for bile-acid-related metabolic diseases." (PMID 38255993, 2024). "Krüppel-like factor 15 (KLF15) is a transcription factor involved in several metabolic diseases, but its role in AKI and ferroptosis remains unclear." (PMID 37833977, 2023). "Together, KLF15 may be a major therapeutic target for BAs-related metabolic diseases." (PMID 36937859, 2023).
cardiovascular diseases (5 papers, 2017 to 2025). "As a member of the KLF family, KLF15 mainly functions as a transcription repressor, the alteration of whose expression is associated with numerous diseases, including cardiovascular disease, metabolic disorders, and cancer." (PMID 33869197, 2021). "Research suggests that in cardiovascular diseases, BCAA metabolism is disrupted due to downregulation of Krüppel-like factor 15 (KLF15), mediated by TAK1 and p38 MAPK signaling." (PMID 40052157, 2025).
kidney (2 papers, 2023). "Our study showed that KLF15 expression was reduced in kidney tissues of AKI mice, and KLF15 knockout exacerbated folic acid-induced ferroptosis and kidney injury." (PMID 37833977, 2023). "Therefore, the KLF15 gene is a key factor in regulating liver metabolism, and interference with the expression of the KLF15 gene may result in changes in HFD-induced liver lesions." (PMID 36937859, 2023).
KLF15 also shares sentences with these, for which no sentence is quoted: hypertrophy (4 papers); atrial fibrillation (3); Atrophy (3); airway hyperresponsiveness (2); amyotrophic lateral sclerosis (2); cardiac arrhythmias (2); endometrial cancer (2); glomerulosclerosis (2); idiopathic pulmonary fibrosis (2); Infertility (2); Skeletal muscle atrophy (2); age (1); alcohol addiction (1); Ataxia (1); Becker muscular dystrophy (1); bronchopulmonary dysplasia (1); cardiac disease (1); Cirrhosis (1); diabetic cardiomyopathy (1); esophageal squamous cell carcinoma (1); Glucose intolerance (1); hepatoma (1); inflammation (1); ischemic stroke (1); juvenile dermatomyositis (1); kidney injury (1); liver (1); lung diseases (1); neuromuscular disease (1); non-small cell lung carcinoma (1).
A further 7 diseases each share a sentence with KLF15 in 1 paper.